CDK2 (cyclin dependent kinase 2)
Diseases named in the same sentence as CDK2 in open-access papers (continued):
Sharing a sentence is not in itself a finding about the gene and the disease.
cancer (continued). "In human cells spanning many cancer types, we have shown that alongside blocking proliferation, mifepristone strongly inhibited the activity of Cdk2." (PMID 25252652, 2015). "CKS1B is overexpressed in several cancers and binds to cdk2, overcoming the replicative barrier imposed by activated oncoproteins." (PMID 25477524, 2015). "The investigated carcinomas used the signaling cascade via increased expression of CDK2 and CCNE1 to drive cell cycle transition." (PMID 26008974, 2015). "Significantly, CD44+/CD24−/Low CSCs displayed a higher resistance to methotrexate while they where highly sensitive to the Cdk2 inhibitor SU9516 compared to bulk SUM149PT cancer cells." (PMID 24970653, 2014). "Other studies using a candidate approach also identified several cell cycle kinases as MYC-synthetic lethal genes in different types of cancer, including CDK2, CDK1 and aurora-B kinase." (PMID 24444383, 2014). "In two examples of mutations in Cyclin-dependent kinase 2 (CDK2) and Diacylglycerol kinase, beta (DGKB) genes, we show how the in vivo assay reveals novel insights on the functions of these genes in cancer." (PMID 25260652, 2014). "In “pathways in cancer”, both the transcriptomic results and qPCR data revealed that 7 DEGs, including cdk4/6, ptenl, fu, cdk2, ral, faks, and elongb, are all upregulated by Ras1CA, while fakl is downregulated." (PMID 24606580, 2014). "Further, the effects of SAP155/FIR/ FIRΔexon2 on the expression of P27, cdk2/cyclinE, and P89 provided novel information on a regulatory circuit that is important for cell growth and cancer progression." (PMID 24811221, 2014). "Some cancer cells however possess resistance to CDK2 inhibition, as shown by a unique upregulation of CDK2 target proteins and preexisting cellular polyploidy in cancer cells." (PMID 25477962, 2014). "The effect of CDK2 inhibitors on the proliferation of various cancer cells has been extensively studied, but less attention has been paid to the ability of CDK2 inhibitors to modulate the expression of transcription factors responsible for pluripotency." (PMID 25477962, 2014). "On the other hand, it has been shown that p21Cip1/Waf1 is cleaved by Caspase-3, being this a prerequisite for cell death, converting cancer cells from growth arrest to undergoing apoptosis through activation of CDK2." (PMID 25286245, 2014). "The Akt and MAPK pathways are involved in the regulation of cell cycle progression and the S-G2 phase transition of cancer cell cycle is controlled by CDK2/Cyclin A complexes." (PMID 24810113, 2014). "Cyclin-dependent kinase 2 associate protein 1(CDK2-AP1) is a specific negative regulatory protein for CDK2, is important in the cancer cell cycle." (PMID 25550687, 2014). "Various specific CDK2 inhibitors have been shown to be effective in inducing apoptosis and reducing proliferation of various cancer cells." (PMID 25477962, 2014). "Overall, the ability of CDK2 and CDK4 to mediate various malignant phenotypes that play important roles in cancer biogenesis has prompted the development of CDK2 or CDK4 specific inhibitors." (PMID 23886499, 2013). "The results show that replication-competent Adwt and Adhz63 induce cyclin EL expression and increase the formation of cyclin EL/CDK2 complex in A549 cancer cells, indicating that the cyclin EL induced in Ad-infected cells strongly associates with CDK2." (PMID 23437375, 2013). "This agreed our findings with Ros showing that specifically inhibiting CDK2 with siRNA significantly repressed viral production, which correlated with the decreased CDK2 activation and phosphorylation on pRb in cancer cells." (PMID 23437375, 2013). "Considering that the control of G1 exit is generally abnormal in cancer cells, we verified the role of CDK2 in Ad replication in WI-38 human diploid cell line that was derived from the normal embryonic lung tissue." (PMID 23437375, 2013).
cancer (continued). "Taken together, these data provide evidence that tumours harbouring 19q12 amplification have more than one 'driver' and suggest that cancer cells with CCNE1 amplification depend on CDK2 expression and kinase activity for their survival." (PMID 22433433, 2012). "In summary, we have shown that chrysin posses potent invitro anti-cancer activity by suppressing cell proliferation, inducing G1 cell cycle arrest with the upregulation of p21 and decrease in cyclin D1, cdk2 protein levels." (PMID 22591439, 2012). "Cancer cells with CCNE1 amplification were shown to be dependent on CDK2 expression and kinase activity for their survival." (PMID 22433433, 2012). "siRNA-mediated CDK2 silencing resulted in a significantly higher reduction in cell survival of cancer cells harbouring CCNE1 gene amplification than in cancer cells devoid of amplification of this gene (t-test, P < 0.05)." (PMID 22433433, 2012). "Here we have demonstrated that CCNE1 is a driver of the 19q12 amplicon and that cancer cells harbouring CCNE1 gene amplification display an increased sensitivity to CDK2 RNAi-mediated silencing and chemical inhibition." (PMID 22433433, 2012). "The paradigm relating cell cycle control, cyclin-dependent kinases and cancer has changed from our classical understanding, however, with reappraisal of the mandatory requirement of Cdk2, Cdk4 or Cdk6 for normal cell division." (PMID 21668989, 2011). "The dual control of CDK2 on cell proliferation and apoptosis makes it an interesting anti-cancer target." (PMID 21552547, 2011). "We know that p21 binds to CDK2, inhibiting kinase activity in various types of cancer cells and inducing cell cycle arrest at G1 with subsequent cellular senescence." (PMID 21285982, 2011). "Deregulation of the cyclin-dependent kinase 2 activity by cellular and external factors leads to many diseases like cancers." (PMID 21188035, 2010). "Previous studies have indicated that Akt-mediated p21 phosphorylation can result in p21 localizing to the cytoplasm in Her2-positive cancer cells and also inhibit p21 binding to cdk2." (PMID 20598155, 2010). "A considerable amount of investigations have been carried out to develop inhibitors that target CDK2/cyclin A for treating cancer, and several CDK2/cyclin A inhibitors have been under clinical evaluation." (PMID 21152296, 2010). "Studies in other cancer cell lines measuring cell cycle effects of individual CDK2 depletion showed little change in cell cycle profiles of asynchronous cells due to compensation by other CDK family members, including CDK1 and CDK4/6." (PMID 20010939, 2010). "The cancer group has significantly higher levels of autoantibodies to c-myc, Cyclin A, and CDK2 compared to the solid nodule group." (PMID 20504322, 2010). "C-myc, cyclin A, cyclin B1, cyclin D1, CDK2, and survivin contributed to the separation between the cancer and non cancer groups." (PMID 20504322, 2010). "We report the successful identification of a novel lead compound that displays selective inhibitory effects on CDK2 activity, cancer cell proliferation, and tumor progression in vivo." (PMID 19194508, 2009). "Cyclin E over expression is a common feature in cancer, suggesting that cyclin E/CDK2 deregulation contributes to tumorigenesis." (PMID 17169158, 2006). "To answer this question, we have to determine if Rb wild type cancer cells require Cdk2 and Cdk4 activities throughout tumor progression." (PMID 16759374, 2006). "These suppress the breakdown of cyclin B1 and CDK2 to stop the development of cancer." (PMID 40078339, 2025). "Therefore, CDK2 inhibition represents a promising therapeutic alternative for cancers with CDK2/cyclin E-dependency." (PMID 39935426, 2025). "These cancer cells were resistant to apoptosis and proliferated despite CDK2 inhibition." (PMID 40232858, 2025).
cancer (continued). "The combined treatment of a TTK inhibitor with a CDK2 antagonist might eradicate persistent cancer cells that follow single-agent CDK2 inhibitor treatment as reported in this study." (PMID 40232858, 2025). "Therefore, CDK2 is increasingly recognised as a potential therapeutic target, prompting substantial interest in the development of CDK2 inhibitors for cancer treatment." (PMID 40905579, 2025). "Similarly, due to the fact that CDK2 regulates cell cycle progression through its interaction with other cyclins, it is vulnerable for defects regarding their expression, especially for cancers." (PMID 40649898, 2025). "This study provides the first evidence that pharmacological concentrations of VC induce the expression of pro-apoptotic proteins such as Apaf-1 and caspases -7 and -9, while inhibiting cancer cell survival proteins like Bcl-2, cyclins D and B1, CDK2, Akt, pI3K, and mTOR." (PMID 40149617, 2025). "In addition, CDK2 plays a significant role in suppressing oncogene-induced senescence since CDK2 suppression-induced senescence was detected in various human cancer cell types." (PMID 40563707, 2025). "We found that after tail vein injection of anti-PD-1 antibodies into mice bearing WT or Cdk2-/- cancer cells, the Cdk2-/- tumors plus anti-PD-1 Ab grow slower than Cdk2-/- PBS group, but there was no statistical difference in WT tumors with or without anti-PD-1 Ab treatment." (PMID 40557162, 2025). "The findings suggest that CDK2 inhibition, in combination with anthracyclines or anti-PD-1 therapy, may offer a therapeutic strategy in cancer treatment." (PMID 40557162, 2025). "The inhibition of cdk2 and the increase in p21 expression suggest that the treatments may also arrest the cell cycle at the G1 phase, preventing the proliferation of cancer cells." (PMID 40248096, 2025). "This redundancy in the control of RB phosphorylation suggests that the effectiveness of CDK4/6is may be improved in some cancers by combining CDK2 inhibition with CDK4/6is." (PMID 40282469, 2025). "Molecular docking studies revealed that the newly designed compounds exhibited better binding affinities (−7.2 to −9.8 kcal/mol) to key cancer-related targets (CDK2, EGFR, and Tubulin) compared to the reference drug and the most active molecule (molecule 39) in the dataset." (PMID 40526618, 2025). "This confers a persistent cancer cell population, despite ongoing CDK2 treatment." (PMID 40232858, 2025). "Here we show that cancer context tunes the response to different CDK2 inhibitors." (PMID 39924553, 2025). "Overall, this study underscores two fundamentally distinct features of response to CDK2 inhibitors that are conditioned by tumor context and could serve as the basis for differential therapeutic strategies in a wide range of cancers." (PMID 39924553, 2025). "Cyclin dependent kinase 2 (CDK2) regulates cell cycle and is an emerging target for cancer therapy." (PMID 39924553, 2025). "In marked contrast to the actions of pharmacologic or genetically mediated repression of CDK2 activity in aneuploid cancer cells, normal human alveolar epithelial cells (HAEC) proved resistant to the growth inhibitory or proapoptotic effects of this inhibition." (PMID 40232858, 2025). "CDK2 inhibition of tumor-bearing mice produced polyploid cancer cells in vivo." (PMID 40232858, 2025). "Inhibiting CDK2 has been explored as a strategy to halt the growth of cancer cells." (PMID 39861131, 2025). "Genetic alterations in CDK2 are rarely identified in human cancers." (PMID 39800748, 2025). "In certain tumors, cancer cells can continue to grow despite the inhibition of CDK2." (PMID 40486867, 2025). "Genes encoding proteins such as cyclin-dependent kinase 2 (CDK2), cyclin-dependent kinase 4 (CDK4), CDC28 protein kinase 1B (CKS1B), cyclin A2 (CCNA2), and cyclin D1 (CCND1) play key roles in promoting cell division and cancer progression." (PMID 41003013, 2025).
cancer (continued). "Phytochemicals that target the enzyme CDK-2 may prevent the progression of cancer through halting the spread of tumors and killing off cancer-causing stem cells by influencing their activity." (PMID 40901864, 2025). "By simultaneously inhibiting CDK4/6 and managing CDK2 activity, it may be possible to induce cell cycle arrest more effectively and prevent the proliferation of cancer cells that have adapted to evade conventional regulatory mechanisms." (PMID 41465342, 2025). "Which makes CDK2 inhibitions is a desirable target for cancer treatment." (PMID 38365746, 2024). "In many previous studies HDAC inhibitors as SB have shown an influence on cell cycle regulating proteins, like p21, p27 (cyclin-CDK-inhibitors), CDK1, CDK2 (cyclin-dependent-kinases), and an induction of cell cycle arrest in G1/S and M/G2-phase in various cancer cells." (PMID 38650948, 2024). "Therefore, CDK2 is a potential cancer therapy target with abnormal levels or activity of many tumors." (PMID 38531837, 2024). "The interaction between PI3K-AKT and CDK2-Rb is indisputably advantageous for cancer cell growth." (PMID 38755637, 2024). "Moreover, their insensitivity to CDK4/6i indicates the primacy of CDK2 in driving the G1 to S transition in CCNE1-amplified cancer cells." (PMID 38047585, 2024). "In addition to RNAi, small molecule inhibitors like Adavosertib, a WEE1 inhibitor, have been explored for their ability to inhibit cyclin E/CDK2 complexes, slowing down cell cycle progression in cancers with CCNE1 amplification." (PMID 39591374, 2024). "The varied functions of CDK2 within cellular proliferation and survival pathways render it a highly compelling target for mechanism-driven and low-toxicity therapeutic approaches in the field of cancer treatment." (PMID 38321062, 2024). "Furthermore, CDK2’s interaction with other cell cycle regulators can make cancer cells resistant to standard therapies, complicating treatment." (PMID 38474160, 2024). "This makes CDK2 an attractive target for anticancer drug development, with several inhibitors being explored for their potential to disrupt its activity and thereby control the progression of various cancers." (PMID 38474160, 2024). "Based on results from clinical studies, it has been shown that overexpression of CDK2 may play a role in the development of cancer." (PMID 38321062, 2024). "WEE1 deficiency in cancer cells leads to hyperactivation of CDK1 and CDK2, thereby leading to multiple initiation of replication origins that causes depletion of replication factors, subsequent fork slowing, accumulation of single-stranded DNA and genomic instability followed by accumulation of RPA." (PMID 38279263, 2024). "Whether this is true in CCNE1-amplified cancers, which might be highly CDK2-dependent, remains unclear." (PMID 38047585, 2024). "Previous studies found that CDK2 is over-activated in many types of cancer." (PMID 38365746, 2024). "CDK2 is strongly associated with proliferation in specific cancer types, and since CDK2 binds to cell cycle protein E to promote cell cycle progression, targeting CDK2 may offer new options for the treatment of these human cancers." (PMID 38338471, 2024). "CDK2 is a key regulator of the eukaryotic cell cycle significantly over-activated in many cancers." (PMID 38698063, 2024). "Moreover, this interaction both prevented CDK2 from functioning and induced cancer cells to degrade it." (PMID 39496012, 2024). "The broad functionality of CDK-2 in proliferative and pro-survival pathways highlights its potential as an ideal target for mechanism-based and low-toxicity therapeutic strategies in cancer treatment." (PMID 38184514, 2024). "Inhibiting CDK2 activity has emerged as a potential therapeutic strategy in cancer treatment." (PMID 38474160, 2024). "It is known that CDK2 has significant implications for cancer treatment and cellular aging." (PMID 39351221, 2024).
cancer (continued). "Despite these points, controversy about the therapeutic relevance of the CDK2 kinase as a target in cancer therapy persists for a variety of valid reasons, and the availability of a selective CDK2 inhibitor would help resolve a number of these outstanding questions." (PMID 38047585, 2024). "CDK2 is an attractive target for cancer therapy due to its key role in cell cycle progression." (PMID 39597689, 2024). "The oncogenic activity of the cyclinE/CDK2 complex is observed in cancer." (PMID 37240338, 2023). "Targeting the oncogenic complex cyclinE/CDK2 has been proposed as a promising cancer therapy." (PMID 37240338, 2023). "Indeed, several studies have demonstrated the potential of CDK2 inhibition in cancer treatments both as a monotherapy and as part of combination therapies." (PMID 37049714, 2023). "Intriguingly, CDK2 inhibition caused a statistically significant increase in single centrioles rather than intact centrosomes with two centrioles in cancer cells having chromosome rings or multipolarity." (PMID 38031910, 2023). "Interestingly, numerous studies have reported that phytotherapy exerts anti-cancer effects via CDK2-mediated pathways." (PMID 37608369, 2023). "Indeed, SIRT5 blocks the cell cycle of cancer cells at the G1/S phase by negatively modulating cyclin dependent kinase 2 (CDK2) and inhibiting glycolysis." (PMID 36980194, 2023). "In addition, TQ has been reported to induce cell cycle arrest through the inhibition of cyclin E, cyclin D, and cyclin-dependent kinase 2 (CDK-2) in various cancers, as reviewed by our research group." (PMID 37762557, 2023). "Cyclin-dependent kinase 2 (CDK2) is considered a promising drug target for cancer therapy." (PMID 37626747, 2023). "Intriguingly, CDK2 inhibition produced cancer cells with chromosome rings." (PMID 38031910, 2023). "In addition, a significant reduction in CDK2 mRNA expression was observed across all tested pan-cancer cell lines upon the pharmacological co-inhibition of PLK1 and ACLY." (PMID 37958642, 2023). "CDK2 regulates the cell cycle from the late G1-phase and throughout S-phase by interacting with and phosphorylating proteins in cell signaling pathways, which can lead to cancer cell proliferation." (PMID 37822691, 2023). "CDK6 is a homologue of CDK2, highly similar sequences and structural topology with CDK2 that regulates cell cycle progression, which plays an important role in the progression of various types of cancer." (PMID 36342274, 2023). "Future work is warranted to discern the different outcomes within CDK2-inhibited cancer cells." (PMID 38031910, 2023). "Despite the debated role of CDK2 in cancer development, recent studies indicate that targeting CDK2 specifically could offer therapeutic benefits in certain cancers." (PMID 37626747, 2023). "OLA1 has been reported to be connected with cell cycle as well as apoptosis in HCC, which promotes tumor development by binding with p21 and stimulating the expression of CDK2, knocking down its expression contributes to G0/G1 phase arrest and enhancing apoptosis of cancer cells." (PMID 36463115, 2022). "Consequently, the development of novel CDK-2 inhibitors has drawn the attention of the research community because of the expected activity of these compounds against a wide range of cancer cell lines." (PMID 36505739, 2022). "Due to the heterogeneity of TNBC cell lines we hypothesized that the interaction between CDK2 and palbociclib may be a general dependency and could therefore be applied broadly to other cancer types." (PMID 36067171, 2022). "Correlation analysis and cell biological experiments showed that NR1H4 expression was positively associated with Cyclin E2 and CDK2, which indicated NR1H4 may play its oncogenic role in cancer by regulating CCNE2." (PMID 36123627, 2022).